AQP3 (aquaporin 3 (Gill blood group))
Diseases named in the same sentence as AQP3 in open-access papers (continued):
Sharing a sentence is not in itself a finding about the gene and the disease.
skin tumor (20 papers, 2011 to 2025). "It has also been observed that AQP3 is highly expressed in human squamous cell carcinoma and that AQP3-deficient animals exhibit a reduction in the development of skin tumours." (PMID 38336645, 2024). "Meanwhile, it is noted that an association between high AQP3 levels and skin tumor formation has been reported." (PMID 38731895, 2024). "AQP3 is the aquaglyceroporin most implicated in tumorigenesis, being aberrantly overexpressed in cancers of different origin, such as skin cancer, colon, lung, liver and pancreatic cancer." (PMID 35187089, 2022). "AQP3 has been associated with cell proliferation in cancer cells, namely in skin tumors where it is highly expressed." (PMID 35187089, 2022). "The principal finding from this report is the remarkable resistance of AQP3-deficient mice to the development of skin tumors." (PMID 35847914, 2022). "A decreased overall survival of cutaneous melanoma patients has been linked to a positive AQP1 expression, and an increased AQP3 expression in skin cancer patients and lung cancers has been detected." (PMID 36233821, 2022). "And mice deficient in AQP3 exhibit a strong resistance to skin tumors." (PMID 40760228, 2025). "AQP3 has some diagnostic utility in differential diagnosis of skin tumors." (PMID 34745849, 2021). "The mode of action of Kanglaite is unlike certain ingredients of some cosmetics products which claim to increase epidermal AQP3 expression, and in fact, high AQP3 level may be associated with high risk of skin tumors." (PMID 22211241, 2012). "AQP3-null mice were found to be resistant to the development of skin tumors after exposure to a skin tumor initiator and phorbol ester promoter, exhibiting a reduction in epidermal cell proliferation." (PMID 39941100, 2025). "AQP3 knockout mice can inhibit the development of skin tumours, and tumorigenesis can utilize ATP produced by AQP3-mediated glycerol transport." (PMID 35178393, 2022). "Our findings support the view that the water homeostasis regulated by AQP3 was well maintained during carcinogenesis in most of the skin tumors except basal cell carcinoma, sebaceous carcinoma, and malignant melanoma." (PMID 34745849, 2021). "In our study, we found that most skin tumors, except basal cell carcinoma, sebaceous carcinoma, and melanoma, showed positive AQP3 staining (diffuse in most positive tumors)." (PMID 34745849, 2021). "Hara-Chikuma and Verkman (2008b) have studied a multistage skin tumor model in mice and reported that AQP3 is overexpressed in skin cancer, while AQP-null mice show complete resistance to development of skin cancer." (PMID 32351935, 2020). "Dysregulation of AQP3 and Notch receptors has been reported in several skin diseases, including skin cancer." (PMID 24260356, 2013). "In the studies of AQP3-null mice, AQP3 gene deletion induces the resistance to carcinogen-induced skin tumor." (PMID 22145049, 2011). "Additionally, the knockout of Aqp3 has been found to prevent skin cancer progression in mice exposed to tumor inducers, indicating that AQP3 is a key molecule in skin cancer progression." (PMID 39060229, 2024). "Interestingly, after exposure to a skin tumor initiator, a similar pattern of apoptotic responses was observed in both wild-type and AQP3-null mice." (PMID 35847914, 2022). "In summary, our results showed that AQP3 is expressed in most skin tumors except basal cell carcinoma, sebaceous carcinoma, and malignant melanoma, reflecting the biological characteristic of skin tumors." (PMID 34745849, 2021). "Our findings indicate the function of AQP3 maintained in most skin tumors." (PMID 34745849, 2021). "However, limited information on AQP3 expression in other skin tumors is available." (PMID 34745849, 2021). "In particular, recent studies have correlated AQP3 glycerol permeation with skin tumorigenesis and identified it as being aberrantly expressed in melanoma, suggesting that AQP3 might be a novel target for skin tumor prevention and therapy." (PMID 22624030, 2012).
skin tumor (continued). "AQP3 is the most expressed isoform in human melanoma MNT-1 cells, as reported for human skin tumors." (PMID 32252345, 2020). "In this study, mice lacking AQP3 were resistant to the development of skin tumors after exposure to a common tumor initiator and chemicals such as phorbol ester." (PMID 35847914, 2022). "A study of AQP3 knockout mice revealed that AQP3 was necessary for skin tumor development, since AQP3 knockout mice did not develop skin tumors after exposure to a tumor initiator." (PMID 28991174, 2017).
colon carcinoma (18 papers, 2008 to 2024). "These authors found that under oxidative stress exposure, the AQP3 expression in HCT 116 cells was significantly increased after treatment with 100 μM H2O2 compared to other colon cancer cell lines (Caco-2, HT-29, and SW620)." (PMID 38089478, 2023). "Another study also found that immunohistochemistry scores of AQP3 in colon cancer patients were positively correlated with serum AQP3 concentrations." (PMID 38089478, 2023). "The major finding of this study is that the hormone vasopressin controls the expression and the function of AQP3 in human colon carcinoma cells." (PMID 35874817, 2022). "In this study, we provide novel evidence that AVP controls the expression and the function of AQP3 in human colon carcinoma HCT8 cells." (PMID 35874817, 2022). "Overexpression of AQP3 has been observed in different types of cancer such as lung, pancreas, skin, cornea and colon cancer, where it is involved in cell migration, invasion, proliferation, and EMT." (PMID 35187089, 2022). "AQP3 has been suggested to modulate tumor differentiation in colon cancer patients via the EGFR pathway, but its role remains to be defined." (PMID 32679804, 2020). "AQP3 transcript levels also appeared high, suggesting a gap in knowledge with regard to a possible role in colon cancer." (PMID 32679804, 2020). "Immunohistochemistry analysis of colorectal cancer cells revealed that AQP3 expression is correlated with the degree of differentiation, lymph node metastasis and distant metastasis of colon cancer." (PMID 32662230, 2020). "Prostaglandin E2 (PGE2) causes a marked, rapid decrease in the protein expression of AQP3 in the HT-29 cell line, which is derived from human colon cancer." (PMID 30925715, 2019). "The expression intensity of AQP3 was correlated with tumor differentiation and metastasis in colon cancer patients." (PMID 25886458, 2015). "The migration of colon cancer cells can be inhibited by AQP3-specific inhibitor, as well as EGFR pathway inhibitors." (PMID 25886458, 2015). "The copper(II) analogue of Auphen, [Cu(phen)Cl2] (Cuphen) was also observed to inhibit AQP3, although less potently than Auphen, and to reduce glycerol permeation in AQP3-expressing melanoma and colon cancer cells, leading to anti-proliferative effects and cell migration impairment." (PMID 35187089, 2022). "In addition, a Chinese research team highlighted that preoperative serum AQP3 levels were significantly elevated in patients diagnosed with colon cancer, demonstrating its clinical value for the early screening of colon cancer." (PMID 35972604, 2022). "Additionally, the expression of these aquaporins was increased in cancer tissues, and the inhibition of AQP3 permeability reduced tumor progression in a murine colon cancer model." (PMID 34829727, 2021). "AQP3 expression was shown to promote the proliferation and migration of colon cancer cells." (PMID 32662230, 2020). "Inhibition of AQP3 in bladder cancer cell lines or knockdown of AQP3 in breast and colon cancer cell lines decreases intracellular platinum concentration and attenuates the pro-apoptotic effects of nucleoside analog (5’ DFUR and gemcitabine) treatment, respectively." (PMID 26799320, 2016). "It provided a new therapeutic strategy in colon cancer by blocking AQP3 and EGFR pathway." (PMID 25886458, 2015). "The colon cancer had higher expression of AQP3 compared to the normal tissue." (PMID 25886458, 2015). "Inhibition of AQP-3 could reduce colon cancer or pancreatic cancer cell migration and invasion." (PMID 33209198, 2020). "Higher levels of expression of peroxiporins AQP1, AQP3 and AQP5 in colon cancer cell lines correlated with better protection from oxidative insults, even when the background activity of antioxidant defense system components remained unchanged." (PMID 38451099, 2024).
colon carcinoma (continued). "LINC01567 can regulate the proliferation of colon cancer stem cells (CSCs) through sponging miR-9, resulting in the modulation of Cyclin D2 (CCND2) and the regulation of aquaporin 3 (AQP3), which can be regulated by the CREB molecule in the cAMP–PKA pathway." (PMID 37888204, 2023). "In particular, AQP1, AQP3, and AQP5 were found to be correlated with lymph node metastases in colon cancer patients." (PMID 34829727, 2021). "In studies of AQP1, AQP3 and AQP5 expression, some of these proteins were detected in colon cancer tissues and colorectal cancer cells, indicating that they play a role in colorectal cancer development." (PMID 32662230, 2020). "AQP3 is expressed in colon cancer, and both epidermal growth factor (EGF) and oestrogen, which are known to be involved in the occurrence of cancer, are considered upstream regulators of AQP3 expression." (PMID 32662230, 2020). "As a result, it was found that astaxanthin significantly increased the mRNA expression level of AQP3 in human colon cancer HT-29 cell line (data not shown)." (PMID 32932769, 2020). "Hepatic cancer expresses similar types of AQPs with colon cancer, e.g. AQP1, AQP3, AQP5, and AQP9." (PMID 25886458, 2015). "Third, the expression of AQP5, not AQP1, or AQP3, was found to be associated with Ras/ERK/Rb pathway activation in colon cancer cell lines and was linked with liver metastasis in colon cancer patients." (PMID 18478076, 2008).
lung carcinoma (18 papers, 2015 to 2025). "Our data validated AQP3 as a lung cancer susceptibility gene in this locus and suggested potential involvement of epithelial-specific cCREs in its regulation." (PMID 39266564, 2024). "In non-small cells, lung cancer downregulation of AQP3 is associated with a relevant suppression of cell growth." (PMID 35874817, 2022). "Notably, AQP3 levels are associated with lung cancer progression, specifically maintenance of water homeostasis and differentiation of lung carcinoma." (PMID 39611488, 2025). "Therefore, the present study investigated the anticancer and anti-angiogenesis potential of MP06 in association with AQP3 expression in lung cancer cells and a zebrafish model." (PMID 39611488, 2025). "AQP3 expression affects lung cancer cell properties including proliferation, migration, metastasis and angiogenic potential." (PMID 39611488, 2025). "The present study demonstrated that AQP3 was more highly expressed in lung cancer than in normal tissues." (PMID 39611488, 2025). "The Kaplan-Meier graph confirmed that the survival rate of patients with lung cancer and high AQP3 expression was low." (PMID 39611488, 2025). "In lung cancer, Aquaporin 3 (AQP3) promotes M2 polarization and upregulates IL-6 secretion via the PPARγ/NF-κB signaling axis, thereby exacerbating glucose metabolic disorders through the IL-6R pathway." (PMID 41459510, 2025). "In experimental NSCLC, the antitumour benefits of AQP3-targeting shRNA were found, as shown by the suppression of AQP3 ablation for lung cancer development and longer life in preclinical experiments." (PMID 38336645, 2024). "It is likely that AQP3 regulates the biological processes of lung carcinoma cells and is essential early in the development of lung ADCs." (PMID 38336645, 2024). "Knocking down AQP3 in M2 macrophages inhibited cell cycle progression, proliferation, and migration of lung cancer cells, while AQP3 overexpression promoted these cell activities in M2 macrophages." (PMID 39060229, 2024). "AQP3 can, therefore, through inhibition of apoptosis and reduction in differentiation support stemness of these lung cancer cells, which implies the use of APQ3 for determining the malignant potential and recurrence of the primary disease." (PMID 33947079, 2021). "AQP3 was found to be overexpressed in lung cancer and played a critical role in tumor angiogenesis, progression, and metastasis." (PMID 34708074, 2021). "On the contrary, low levels of AQP3 affect stemness maintenance in human lung cancer stem cells, upregulating the Wnt/GSK3β/β-catenin pathway and Hippo pathway and resulting in altered differentiation and apoptotic processes." (PMID 33924772, 2021). "Here, for the first time, we propose that miR‐874 targets AQP3 in lung cancer and inhibits cellular processes through AQP3." (PMID 32301290, 2020). "Increased AQP3 also promoted angiogenesis in lung cancer through HIF-2α–VEGF, and invasion via AKT–MMP pathways." (PMID 32679804, 2020). "The role of AQP3 in EGFR-dependent cell signaling and cancer progression was investigated in human squamous cell carcinoma and human lung cancer cell lines, both expressing high concentrations of AQP3 and EGFR." (PMID 30893772, 2019). "AQP3 knockdown in skin and lung cancer cell lines reduced EGF-induced H2O2 influx, and attenuated EGF signaling cascades, reducing migration and growth." (PMID 29922644, 2018). "The anticancer effects of shRNA-targeting AQP3 were observed in experimental NSCLC, further evidenced by the inhibition of AQP3 deletion for lung cancer growth and prolonged survival in preclinnical studies." (PMID 25886458, 2015). "Furthermore, it was confirmed that AQP3 was more highly expressed in lung cancer than in normal lung tissue using Gene Expression Profiling Interactive Analysis web server (gepia.cancer-pku.cn/detail.php?gene=AQP3, accessed April 24, 2024)." (PMID 39611488, 2025).
lung carcinoma (continued). "Developing a profound and evidence-based understanding of how AQP3 and 4 are interacting with signaling pathways that are known to have a crucial relevance in lung cancer development and progression will be extraordinarily important for the detection of novel therapeutic strategies." (PMID 36233821, 2022). "Expression of AQP1, AQP3, and AQP5 was negatively associated with the degree of cellular differentiation, and higher expressions of AQP1 and AQP5 were observed among invading lung cancer cells with metastasis." (PMID 35847914, 2022). "Thus, AQP3 influences the expression of canonical Wnt signaling cascade, eventually affecting the proliferation and metastasis formation in lung cancer cells." (PMID 33924772, 2021). "A parallel increase in levels of AQP3 could point to a gap in knowledge regarding a possible role in lung cancer." (PMID 32679804, 2020). "AQP3 may be involved in the initiative of angiogenesis in lung cancer through HIF- 2α-VEGF pathway, lung cancer cell invasion partly by the AKT-MMPs pathway, cellular glycerol uptake, or mitochondrial ATP formation." (PMID 25886458, 2015). "It is possible that AQP3 may regulate biological functions of lung cancer cells and be required in the early stage of lung ADC development." (PMID 25886458, 2015). "Therefore, we concluded that IL-6 might serve as a key downstream molecule of AQP3, exerting regulatory effects on the progression and glucose metabolism of lung cancer cells." (PMID 39060229, 2024). "Therefore, we believe that the AQP3 role in lung adenocarcinoma tissue is not limited to its direct effect on cancer cells but rather its ability to indirectly mediate the polarization of M2 macrophages, which can affect the occurrence and progression of lung cancer." (PMID 39060229, 2024). "For instance, AQP3-mediated H2O2 transport was shown to be involved in EGF-induced cell signaling in squamous cell carcinoma (A431) and lung cancer (H1666) cell lines, and AQP3 blockage suppresses the cell response to EGF." (PMID 39125952, 2024). "A later follow-up study reported that AQP1, AQP3, and AQP5 were detected in 71%, 40%, and 56% of resected lung cancers, respectively." (PMID 35847914, 2022). "Overexpression of AQP1, AQP3 and AQP5 has been the major focus of papers published in the lung cancer field." (PMID 32679804, 2020). "The inhibition of AQP3 by RNA interference retarded the growth and invasiveness of XWLC-05 lung cancer cells and decreased the activity of matrix metalloprotease-2 (MMP2)." (PMID 30555637, 2018). "Positive correlations between AQP3, MMP2, and MMP9 and cancer invasiveness also occur in lung cancer." (PMID 29922644, 2018). "AQP3 may have a role in lung cancer angiogenesis via the HIF- 2α-VEGF route, lung cancer cell invasion via the AKT-MMPs pathway, cellular glycerol uptake, or mitochondrial ATP production." (PMID 38336645, 2024). "In the case of lung cancer, although AQP3 is expressed in the normal respiratory tract and plays an important role in the maintenance of water homeostasis, similar to AQP1, expression of AQP3 also participates in pulmonary carcinomatosis." (PMID 35847914, 2022). "Moreover, AQP3 appears to be involved in the process of angiogenesis in lung cancer through the HIF-2α-VEGF pathway, and AQP3 does also play a role in cell invasion, partly via the AKT-MMPs pathway." (PMID 36233821, 2022). "Further, we showed that AQP3 was distinctively expressed in the cytoplasmic membrane of cancer cells in 65 of 79 lung carcinoma biopsies, whereas in non-neoplastic lung samples, AQP3 was localized in basolateral plasma membranes of the surface epithelium." (PMID 36233821, 2022). "In lung cancer it is common to see overexpression of AQP1, AQP3, AQP4, and AQP5." (PMID 30555637, 2018). "AQP1, AQP3, AQP4 and AQP5 are over-expressed in lung cancer." (PMID 25886458, 2015). "However, the relationship between AQP3 and macrophages in lung cancer has not been explored." (PMID 39060229, 2024).